POSTN (periostin)
Diseases named in the same sentence as POSTN in open-access papers (continued):
Sharing a sentence is not in itself a finding about the gene and the disease.
lung cancer (continued). "Silencing of POSTN could inhibit the migration and in vitro invasive potential of lung cancer cells, most probably via the downregulation of MMP-2 expression and activity as well as integrin-signaling related proteins." (PMID 35163164, 2022). "Based on our findings, POSTN can be a promising prognostic biomarker for lung cancer." (PMID 35508298, 2022). "Moreover, increased CD274, PDCD1, and CTLA4 levels are strongly related to the overexpression of POSTN in lung cancer, especially LUSC." (PMID 35508298, 2022). "Collectively, these results indicate that overexpression of POSTN may be an independent prognostic factor for lung cancer patients." (PMID 35508298, 2022). "Furthermore, there was a close correlation between the level of POSTN and immune infiltration in lung cancer, especially in LUSC." (PMID 35508298, 2022). "In addition, several studies on lung cancer show that periostin is unexpectedly downregulated in malignant tissues compared to normal tissues." (PMID 36224629, 2022). "A statistically significant decrease in invasiveness was found in lung cancer cells, silencing POSTN (A549.shRNA) compared to the control cells (A549.CTRL) at the 24th, 48th, and 72nd hours of the experiment (*** p < 0.001, respectively; Bonferroni multiple comparisons)." (PMID 35163164, 2022). "Furthermore, to study the biological role of POSTN in the progression of NSCLC, we used shRNA to silence the expression of POSTN in lung cancer cells (the loss of function phenotype model)." (PMID 35163164, 2022). "POSTN has been shown to be strongly correlated with the poor prognosis of lung cancer patients." (PMID 35508298, 2022). "Moreover, the upstream regulatory mechanism of POSTN in LUSC was investigated here to further study the mechanism of lung cancer." (PMID 35508298, 2022). "The present study aims to determine epithelial POSTN expression in NSCLC and to assess associations with clinicopathological factors and prognosis as well as to explore the effects of POSTN knockdown on tumor microenvironment and the migration and invasion of lung cancer cells." (PMID 35163164, 2022). "In summary, POSTN may regulate lung cancer cell invasiveness by modulating the expression of MMP-2 and may represent a potential target for novel therapeutic intervention for NSCLC." (PMID 35163164, 2022). "Furthermore, to the best of our knowledge, this is the first study to show a possible relationship between the knockdown of POSTN expression in lung cancer cells in vitro and the downregulation of MMP-2." (PMID 35163164, 2022). "Therefore, in this study, we used informatics analysis to investigate the correlation between POSTN levels and the prognosis of lung cancer using existing data from The Cancer Genome Atlas (TCGA)." (PMID 35508298, 2022). "Therefore, this study aims to analyze the effect of POSTN-silencing on migratory and invasiveness of lung carcinoma A549 cells and the expression of tumor microenvironment factor MMP-2 and integrin-signaling-pathway-related proteins." (PMID 35163164, 2022). "Taken together, our study suggests that secreted periostin from tumor cells can be detected in the air-way fluid, indicating that it may play a tumorigenic role in lung cancer development." (PMID 32719746, 2020). "The expression of periostin was detected in all subtypes of lung cancers." (PMID 32719746, 2020). "In addition, we noticed significantly upregulated POSTN mRNA in CAFs compared to lung cancer cells and NMLC." (PMID 32987711, 2020). "Our finding of variable expression of periostin in lung cancers may be due to several factors, such as different detection techniques used in the assay and the relatively small sample size in our study." (PMID 32719746, 2020). "For this reason, the pro-metastatic effects of periostin may also play a role in promoting intrapulmonary metastasis of lung cancer and this mechanism warrants investigation." (PMID 33014869, 2020).
lung cancer (continued). "However, the functional significances of N-glycoproteins expression in lung cancers, particularly periostin expression in air-way fluid, is still poorly understood." (PMID 32719746, 2020). "Although our findings indicate the possibility that periostin may be a potential prognostic marker in lung cancer patients, the further large-scale study is still needed to validate our findings." (PMID 32719746, 2020). "Our findings provide new insight into the biological role of periostin in lung cancers." (PMID 32719746, 2020). "The role of periostin in lung cancers needs to be further investigated." (PMID 32719746, 2020). "In summary, our results demonstrated that high periostin expression is a strong prognostic factor in lung cancer, and that periostin secreted by adjacent fibroblasts may promote lung cancer proliferation and invasion." (PMID 30131847, 2018). "Further study is needed to determine whether periostin gives lung cancers the ability to maintain cancer stem cells and to colonize." (PMID 30131847, 2018). "We implanted murine Ex Lewis Lung Carcinoma (Ex3LL) cells into the left thigh muscle of periostin−/− and periostin+/+ mice and allowed four weeks for tumors to develop in the tissue, after which the metastatic nodules in the lungs were examined histologically, macroscopically, and radiologically." (PMID 30131847, 2018). "In addition, expression levels of periostin, Twist and Snail were positively correlated with tumor grade and periostin expression level was positively correlated with Twist and Snail expression in lung cancer specimens." (PMID 28977942, 2017). "The findings indicated that treatment with periostin promoted EMT in lung cancer cells." (PMID 28977942, 2017). "The role of periostin in lung cancer progression is elucidated by the in vivo mouse model." (PMID 28977942, 2017). "Similarly, our results showed that periostin treatment promoted scattering of the lung cancer cells in a dose-dependent manner after 24 h." (PMID 28977942, 2017). "This work provides a novel insight into the mechanism of periostin in lung cancer metastasis." (PMID 28977942, 2017). "Finally, lung cancer cells which were transfected with Twist and Snail siRNA inhibited periostin-promoted migration and invasion abilities." (PMID 28977942, 2017). "We then assessed the prognostic role of periostin in lung cancer by using the TCGA dataset." (PMID 28977942, 2017). "Our findings indicate that changes in periostin expression in lung cancer may serve as a therapeutic target for the treatment of lung cancer metastasis." (PMID 28977942, 2017). "In conclusion, our study elucidates the mechanism of periostin-induced EMT in lung cancer; miR-381 may play a pivotal role in this process." (PMID 28977942, 2017). "Silencing of periostin decreased cell invasion and snail expression in lung cancer cells." (PMID 27034956, 2016). "And importantly, POSTN was implicated to be a negative prognostic marker in breast, lung cancer and colon cancer." (PMID 26930720, 2016). "Therefore, both mRNA expression and protein level of POSTN are increased in lung cancer tissues." (PMID 35508298, 2022). "Thus, POSTN can be identified as the potential target of immunotherapy in lung cancer." (PMID 35508298, 2022). "Therefore, POSTN has a potential to be a novel marker of diagnosis and prognosis of lung cancer." (PMID 35508298, 2022). "Therefore, POSTN may be regarded as a potentially attractive therapeutic intervention target for lung cancer therapy." (PMID 32987711, 2020). "Periostin monoclonal antibody treatment may therefore have potential in lung cancer." (PMID 28977942, 2017). "Periostin (POSTN), found to be upregulated in both breast and prostate cancer stroma, was selected for immunohistochemical validation in a panel of human tumors known to be associated with a prominent stromal reaction (breast, prostate, ovary, colon and lung carcinoma)." (PMID 21611158, 2011).
lung cancer (continued). "To create a specific loss-of-function cellular model using shRNA, we screened the cultured lung cancer cell lines (NCI-H1703, A549, NCI-H522) for the expression of POSTN." (PMID 35163164, 2022). "The fold change in expression showed significant upregulation for the genes BCL3, CD44, PPARD, POSTN, and STAT1 in lung cancer patients compared to asthmatics." (PMID 35406434, 2022). "Two genes, periostin (POSTN) and lumican (LUM) were upregulated in both severe asthmatics and lung cancer patients respectively." (PMID 35406434, 2022). "Lung cancer patient-derived EVs mRNA showed upregulation of SPP1, VEGFA, and POSTN as compared to lung cancer with bone metastasis patients." (PMID 36424413, 2022). "However, the function and mechanism of action of POSTN in lung cancer remain unclear." (PMID 35508298, 2022). "The fold changes in gene expression in lung cancer relative to asthmatic cell lines were in line with the in silico prediction for the genes BCL3, CD44, PPARD, POSTN, FOSB, and STAT1." (PMID 35406434, 2022). "Therefore, the upregulation of Periostin may facilitate immune cell inflammation in lung cancer." (PMID 35508298, 2022). "In summary, our study utilizes an unique approach for the detection of glycoproteins in lung air-way fluids and demonstrates that various proteins, including periostin, are differentially expressed in BAL in lung cancer patients." (PMID 32719746, 2020). "When we transfected lung cancer cells with JNK, p38 and JNK siRNA, we found that periostin-induced promotion of the EMT process was blocked by ERK and p38 siRNAs, but not by the JNK siRNA." (PMID 28977942, 2017). "POSTN gene expression has been claimed to be up-regulated in lung cancer tissues compared to normal lung tissue, and it has been detected by IHC, in lung cancer stroma but not in cancer cells, in support of our findings." (PMID 33905434, 2021). "PN has been previously studied in both IPF and lung cancer, and POSTN up-regulation in both cultured and non-cultured stromal cells derived from IPF as compared to normal lung fibroblasts has been reported." (PMID 33905434, 2021). "Periostin is overexpressed in lung cancer tissues and associated with the prognosis, but the correlation between serum periostin and NSCLC progression, as well as the effects of periostin on survival of NSCLC, has not been fully assessed." (PMID 27816968, 2017). "However, little is known about the mechanisms involved in periostin-induced EMT and metastatic progression in lung cancer." (PMID 28977942, 2017). "Similarly, our IHC results show that high periostin expression is positively correlated with the EMT markers Snail and Twist, as well as stage of lung cancer." (PMID 28977942, 2017). "Silencing of periostin inhibited nicotine-mediated cell growth and EMT in lung cancer cells." (PMID 27034956, 2016). "As periostin is a secreted protein, it is not surprising that elevated periostin levels in serum and pleural effusion have recently been detected in lung cancer patients." (PMID 20534149, 2010). "Notably, POSTN, an important biomarker for Th2-type asthma and a negative prognostic biomarker for lung cancer, was observed to be upregulated in the mixed group." (PMID 35406434, 2022). "Therefore, our results suggest that POSTN promotes the invasive ability of lung cancer cells, at least partly via tumor microenvironment factor MMP-2, highlighting MMP-2 as an effector of POSTN signaling in lung cancer cells." (PMID 35163164, 2022). "However, it is unclear as to whether periostin regulates EMT in lung cancer, or serves as a novel marker in lung cancer prognosis." (PMID 28977942, 2017). "Quantitative gene expression of SPP1, VEGFA, POSTN, RUNX2, CD44, and FOXO1 from lung cancer patients with and without bone metastasis normalized against healthy control." (PMID 36424413, 2022).
colon carcinoma (43 papers, 2006 to 2025). "Clinical studies have identified CAFs co-expressed CD70 and periostin (POSTN) as associated with advanced pT stage in colon cancer or peritoneal metastasis, suggesting a promising therapeutic target." (PMID 40535136, 2025). "Supporting these observations, retrospective analyses of clinical studies have also shown that periostin expression is associated with a trend to metastasize and correlates with angiogenesis in oral, breast, and colon cancers." (PMID 24146092, 2014). "By directly comparing the differentially expressed genes between liver metastatic and primary tumor tissues, POSTN, encoding the periostin protein, was identified as a gene associated with colon cancer and liver metastasis." (PMID 21936950, 2011). "In colon cancer, POSTN has been shown to promote metastatic growth through augmenting cell survival via the Akt/PKB pathway." (PMID 39195230, 2024). "In human colon cancer, periostin can activate the AKT/PKB signaling pathway through the integrins αvβ3 and increase both tumor and endothelial cell survival, which promotes tumor metastasis of colon cancer." (PMID 39682261, 2024). "In mice, upregulation of periostin in breast and colon cancer cells promoted tumor growth and metastasis, respectively." (PMID 38279150, 2024). "Second, the expression of SPOCK1 and POSTN was only verified in several cases of colon cancer due to limited resources." (PMID 36611136, 2023). "POSTN promotes angiogenesis in colorectal malignancies by preventing stress-induced apoptosis and increasing endothelial cell survival, thereby promoting colon cancer metastasis, leading to poor prognosis." (PMID 36816016, 2023). "Clinical studies in oral, breast, and colon cancers reveal that POSTN is well correlated with angiogenesis and metastasis." (PMID 36691359, 2023). "C10_TGFBI displayed high expression of TGFBI, a structural homolog of POSTN, which was found to promote metastasis of colon cancer by enhancing cell extravasation." (PMID 38115703, 2023). "Periostin has also been shown to play an important role in establishing the number and size of liver metastasis in mice with colon cancer." (PMID 36224629, 2022). "The AKT pathway was also involved in periostin-induced expression of survivin and resistance to oxaliplatin and fluorouracil in colon cancer cell lines SW480 and HT-29." (PMID 31412536, 2019). "POSTN also promotes survival in colon cancer via the activation of AKT and to the integrin αvβ3-focal adhesion kinase (FAK)-mediated signaling pathway." (PMID 27708222, 2016). "Recent study has found that periostin silencing significantly increased the number of apoptotic colon cancer cells through supressing the PI3K/Akt/survivin pathway." (PMID 25894199, 2015). "A recent report noted that POSTN activated the Akt/PKB pathway via the αvβ3 integrin to promote cellular survival in colon cancer." (PMID 25874882, 2015). "Colon cancer cells overexpressing periostin showed a strong increase in hepatic metastases in an experimental metastasis model." (PMID 26539408, 2015). "Differential expression of periostin, sometimes of specific splicing isoforms, is observed in a broad range of human cancers, including breast, pancreatic, and colon cancer." (PMID 20109226, 2010). "They found that Periostin promoted metastasis in colon cancer by both preventing stress-induced apoptosis in the cancer cells and augmenting endothelial cell survival to promote angiogenesis." (PMID 17060937, 2006). "Despite multiple markers like α-smooth muscle actin (α-SMA/ACTA2), fibroblast activation protein (FAP), and periostin (POSTN) have been identified in colon cancer, accurately defining cancer-associated fibroblasts remain challenging due to their marked heterogeneity." (PMID 40041860, 2025).
colon carcinoma (continued). "Above results, it is not difficult to find that SPOCK1 and POSTN related to CAF are co-expressed with CD68 and CD206 in colon cancer, which indicates that the CAF-associated POCK1 and POSTN expressions have an important influence on macrophages, especially M2 macrophages." (PMID 36611136, 2023). "The periostin knock-out mice exhibited increased colitis-induced colon cancer development." (PMID 35056404, 2022). "In addition, increased expression of periostin promotes tumor metastasis in gastric, breast, and colon cancers." (PMID 36224629, 2022). "mRNA analysis of CEACAM5, KLK6, and SLC35D3 improves the detection of tumor cells in lymph nodes from patients surgically treated for colon cancer, and, together with POSTN and MUC2, it further allows characterization of the tumor cells with respect to aggressiveness and the tumor cell environment." (PMID 34192710, 2021). "While periostin functions as a ligand for both integrins αvβ3 and αvβ5 to promote adhesion and migration of ovarian cancer cells, it interacts only with integrin αvβ3 to facilitate metastatic growth and angiogenesis of breast and colon cancer cells." (PMID 31137693, 2019). "Periostin has been reported to promote the metastatic growth of colon cancer and the question of whether periostin can induce PCCs to the state of metastatic growth has attracted great attention." (PMID 29163770, 2017). "Moreover, previous report that periostin activated the Akt/PKB pathway via the αvβ3 integrin to promote cellular survival in colon cancer." (PMID 22952986, 2012). "The modest increase in POSTN transcription that we measured in colorectal tumor samples does not match previous data from a semi-quantitative study reporting considerable periostin overexpression in 25/29 pairs of matched normal colon tissue and colon tumor samples." (PMID 18086302, 2007). "Studies have identified periostin as a ligand for integrins αvβ3 and αvβ5 that mediate signaling pathways to enhance cell survival, growth, proliferation, migration, invasion and angiogenesis in various cancer types such as oral, ovarian, breast and colon cancers." (PMID 31137693, 2019). "The human colon cancer tissues data downloaded from TIMER also showed that SPOCK1 and POSTN were positively correlated with CD68 and CD206 in colon cancer tissues." (PMID 36611136, 2023). "We identified seven EMT-related genes (TPM1, LAMC1, POSTN, CCN1, MGP, PCOLCE2, and DPYSL3) with prognostic significance in patients with colon cancer from TCGA and GSE17536 cohorts." (PMID 34180352, 2021). "In addition, our tissue specimens also showed significant overexpression of SPOCK1 and POSTN in tumor cells and CAF for colon cancer." (PMID 36611136, 2023).